CXCR2 (C-X-C motif chemokine receptor 2)
Diseases named in the same sentence as CXCR2 in open-access papers (continued):
Sharing a sentence is not in itself a finding about the gene and the disease.
tumor (continued). "We cross‐examined the genotype of various tumor cells with their ability for automatic pulmonary dissemination, modulated NRAS expression using RNA interference and NRAS overexpression, identified NRAS signaling partners by microarray, and validated them using Cxcr1‐ and Cxcr2‐deficient mice." (PMID 28341702, 2017). "In addition, pre-treatment of lung cell preparations with anti-CXCL5 neutralizing antibody or blockade of its receptor CXCR2 on ESCC cells abrogated the enhanced invasion of ESCC cells attracted by the lung preparations from mice bearing Id1-expressing tumours." (PMID 28186102, 2017). "Moreover, loss of CXCR2 in MDSCs can enhance CD8+ T cells cytotoxicity against tumor cells without affecting the number of CD8+ T cells." (PMID 29383101, 2017). "Similarly, we found that CXCR2 was mainly expressed in tumor lesions instead of mesenchyme." (PMID 28415702, 2017). "However, numerous data support the theory of CXCR2-mediated tumor cell autochthonous growth in PC." (PMID 26771140, 2016). "However, the functional roles of CXCR2 in tumor cells remain the subject of debate." (PMID 26503598, 2015). "Evidences suggest that CXCR2 may participate directly in tumor progression." (PMID 26087179, 2015). "Indeed, when we knocked down Cxcr2, tumor growth was severely impaired." (PMID 26590320, 2015). "After 5 weeks of continuous CXCR2 blockade, we could not only observe a marked reduction in tumour vascularization but importantly tumour incidence and overall tumour burden were reduced, suggesting that CXCL1 is crucial for tumour development at early stages in Stat3ΔLep/ΔLep: KrasG12D/+ mice." (PMID 25734337, 2015). "However, Cxcr2 is also expressed in tumor cells, suggesting that Cxcr2 may play cell autonomous roles in epithelial cells." (PMID 25372289, 2014). "Hence, the loss of p21 or downstream mediators of CXCR2 signaling may transform CXCR2 into a tumor-promoting factor, and this intriguing hypothesis will be further addressed in future studies." (PMID 22789011, 2012). "Moreover, the intensity of CXCR2 membrane and cytoplasmic staining in tumor cells was analyzed." (PMID 22789011, 2012). "In addition, we demonstrated that the tumor source of IL-8 can also result in VE-cadherin phosphorylation and monolayer remodeling, and corroborates previous findings that damaged retina uses IL-8/CXCR2 to favor neovascularization." (PMID 23029099, 2012). "Indeed, adoptive transfer of either wild-type or CXCR2-knockout bone marrow into RETAAD mice revealed that only wild-type G-MDSC were capable of migrating to the primary tumor, demonstrating an absolute requirement for CXCR2 in mediating G-MDSC accumulation in primary tumors." (PMID 22331989, 2012). "Similarly, using a CXCR2 antagonist (aCXCR2) under the same experimental design, we observed a significant reduction in neutrophil infiltration, but the risk of RT-promoted DM was mitigated without compromising local tumor control." (PMID 41486114, 2026). "To evaluate the importance of CXCL1/2 and CFB in driving NET formation under treatments, we applied Dox in combination with SB225002 or LNP023, the inhibitors of CXCR2 (the co-receptor of CXCL1/2) or CFB, respectively, in orthotopic 4T1 and MCF-7 tumor model." (PMID 41480760, 2026). "Their findings confirmed that CXCR3, CXCR2, and CXCR6 are prognostic genes related to AML and its tumor immune microenvironment, offering new insights into AML prevention and treatment." (PMID 40427609, 2025). "CXCR1/CXCR2-armoring has been demonstrated to improve CAR T-cell infiltration, persistence, and tumor control in vivo across several studies." (PMID 41019052, 2025).
tumor (continued). "To further explore the mechanistic role of CXCR2 in immune evasion, we administered exogenous human IL-8 to NOD-SCID gamma (NSG) mice and monitored tumour growth." (PMID 41163221, 2025). "Initial candidates for overexpression have been the chemokine receptors CCR2 and CXCR2 (receptors for CCL2 and CXCL8/IL-8, respectively) for CAR and transgenic TCR T cells, as well as TILs, which revealed increased tumor infiltration in several models." (PMID 41181132, 2025). "Combining PD1 blockade therapy with the inhibition of tumor-secreted CXCL8 and CXCR2-positive M2 macrophages enhances therapeutic efficacy." (PMID 40959082, 2025). "In our study, we propose that IL-8/CXCR2 blockade reduces CD47 expression, which renders tumour cells more vulnerable to macrophage-mediated phagocytosis and increases antitumour immunity." (PMID 41163221, 2025). "Additionally, IL-8/CXCR2 blockade reduces the secretion and macrophage uptake of immunosuppressive lipids—such as ω−3/6 polyunsaturated fatty acids—thereby limiting M2 macrophage polarization and promoting a shift towards a more immunostimulatory tumour microenvironment." (PMID 41163221, 2025). "In this review we described the significance of CXCR1, CXCR2 and CXCR3 receptors and their ligands in tumor processes in MM and MGUS." (PMID 40940985, 2025). "Neutrophils contribute to the establishment of pre-metastatic niches by secreting chemokines such as ARG1, CXCL1, CXCL2, CXCL10, CCL2, CXCR2, and vascular endothelial growth factor A (VEGFA), which attract tumor cells to metastatic sites." (PMID 40227814, 2025). "Immunofluorescence analysis confirmed the coexpression of CXCR2, CXCL15, FAS, and ELOVL5 within the tumours." (PMID 41163221, 2025). "Others have shown in tumor cell lines and animal models that CRC tumor cells express one of the receptors for CXCL8, C-X-C motif chemokine receptor 2 (CXCR2), and that stimulation with CXCL8 induces tumor cell growth and metastasis." (PMID 40895532, 2025). "Trafficking of CAR T-cells into fibrotic tumor beds remains a significant hurdle in PDAC, and the incorporation of chemokine receptors (e.g., CCR2b, CXCR2) into CAR constructs has improved homing to tumor sites in murine models." (PMID 40940995, 2025). "Concurrently, IL-17A enhances CXCL5 production in tumor cells and promotes MDSC migration at the tumor site through a CXCR2-dependent mechanism, facilitating tumor progression and immune evasion." (PMID 40558272, 2025). "CXCL1, through its receptor CXCR2, induces the activation of Snail, which leads to an epithelial-to-mesenchymal transition (EMT) and the migration of tumor cells." (PMID 40427171, 2025). "Enhanced tumor-homing abilities and anti-cancer effectiveness have been demonstrated in CAR-T cells expressing CXCR1, CXCR2, or integrin αvβ6." (PMID 40382583, 2025). "Tumor CXCL1 expression has been shown to drive cancer cell proliferation, migration, invasion and angiogenesis in a CXCR2-dependent manner." (PMID 40108668, 2025). "Given that CXCL8 enhances fibroblast activation via CXCR2 signaling, we propose that SLC6A14 regulates tumor–stroma interactions by sustaining CXCL8 secretion." (PMID 41444422, 2025). "Specifically, knocking down CXCR2 in GFs effectively blocked CAF differentiation and reduced tumor-promoting activity, as shown in our in vitro and in vivo models." (PMID 40490643, 2025). "In GBM, tumor-derived CXCL1/2/3 and CXCR2 promote polymorphonuclear myeloid-derived suppressor cell (PMN-MDSC) mobilization and expansion." (PMID 40948940, 2025). "Tumor-bearing mice treated with JB1-598, had reduced lung metastases and tumor growth, accompanied by reduced expression of PAD4 and CXCR2." (PMID 40801583, 2025).
tumor (continued). "Beyond direct tumor cell signaling, CXCL5 secreted by fibroblasts, macrophages, Schwann cells, and mesenchymal stem cells can recruit CXCR2+ neutrophils, thereby enhancing immune evasion and metastatic niche formation." (PMID 40564091, 2025). "Several groups have sought to target this by armoring CAR T-cells with CXCR1 or CXCR2, both of which are CXCL8 receptors, with the aim of exploiting tumor CXCL8 expression to improve CAR T-cell migration to tumors." (PMID 41019052, 2025). "Tumor cells secrete multiple inflammatory chemokines, primarily mediating neutrophil migration to tumors via CXC chemokines such as CXCR1 and/or CXCR2." (PMID 40963981, 2025). "When cultured with IL-8/CXCR2-expressing cell lines (C4-2B/MDVR, PC3, and NCI-H660), macrophage infiltration was significantly reduced, and the ability of these cells to engulf tumour cells was also impaired." (PMID 41163221, 2025). "Preclinical studies in both NSG and C57BL/6 animal models demonstrated that targeting CXCR2 restored TAM phagocytic activity and significantly reduced tumour growth." (PMID 41163221, 2025). "Therefore, inhibiting CXCR2 reduces the pro-tumor effect of neutrophils and enhances the effectiveness of anti-PD-1 immunotherapy by weakening the immune suppression in the tumor microenvironment, boosting T cell activity, and effectively controlling tumor progression." (PMID 40573881, 2025). "On the other hand, one group found that while CXCR2 armoring enhanced trafficking into the TME, CAR T-cell persistence, and therefore anti-tumor efficacy, remained limited by the immunosuppressive TME." (PMID 41019052, 2025). "IL-8 is produced by tumor cells and cells in the tumor microenvironment, acting through its receptors CXCR1 and CXCR2 to stimulate cell migration, proliferation, and survival." (PMID 40725273, 2025). "Concurrently, integration of chemokine receptors such as CXCR2 or CCR4 enhances CAR-γδT responsiveness to tumor-derived chemokines, improving tumor infiltration and local efficacy." (PMID 41488642, 2025). "The homologous receptor of CXCL3 is CXCR2, which is crucial for the migration of PMN-MDSCs from the bone marrow to the tumor." (PMID 40179015, 2025). "Engineering CAR-NK cells to express chemokine receptors such as CXCR2, CCR5, or CXCR1 has been shown to improve homing to inflamed tumor tissues, particularly in models of renal cell carcinoma and colorectal cancer." (PMID 40723278, 2025). "SB225002 has been confirmed to inhibit tumor growth and significantly suppress TKI-resistant CML cells in mouse xenotransplantation models, indicating that CXCR2-targeted inhibitors represent a promising new therapeutic strategy for CML and TKI-resistant CML." (PMID 40427609, 2025). "Other CXCR inhibitors, such as CXCR1 and CXCR2 antagonists like SCH527123, have demonstrated efficacy in preclinical models of various cancers, highlighting their potential in modulating the tumor microenvironment and reducing metastasis." (PMID 41024311, 2025). "Granulocyte myeloid-derived suppressor cells (g-MDSC’s) are recruited by IL-8, GM-CSF, TNF-alpha, YAP1, CXCR2, and CCL2, conferring tumor immunotherapy resistance to CRC." (PMID 40777019, 2025). "Inhibition of CXCR2 with AZD5069 combined with ICI therapy expands antitumor neutrophil populations and lowers tumor burden in experimental HCC." (PMID 41488615, 2025). "Research indicates that the combination of CXCR2 antagonists and anti-PD1 therapy can reduce tumor burden and extend patient survival." (PMID 40006729, 2025). "Culture supernatant from tumor cell lines also induced NETosis in CXCR1 and CXCR2 signaling-dependent manners." (PMID 38786066, 2024). "To further elucidate the involvement of pivotal regulators CXCL2 in Fn-enhanced tumor growth and macrophage M2 polarization, we used a selective inhibitor SB225002 for CXCR2 (the receptor for chemokines CXCL2)." (PMID 38637499, 2024).
tumor (continued). "qPCR and western blotting identified tumor cells as a significant source of CXCL2 post-cryoablation, suggesting that cryoablation induces tumor cells to secrete CXCL2, which interacts with CXCR2 on neutrophils, increasing their infiltration." (PMID 39648199, 2024). "In general, tumor sites contain expanded PMN-MDSC populations compared to healthy tissue, and the inhibition of their chemotactic receptor CXCR2 can reverse castration resistance." (PMID 39550375, 2024). "The combination of ICIs and CXCR2 antagonists inhibits the enrichment of MDSCs in the TME and improves the potency of CTL to further improve the anti-tumor effect." (PMID 39766230, 2024). "In a study for tumor-stromal interaction in pancreatic tumors, transwell assays showed PDAC cells and CAFs attracted each other in a CXCR2-dependent manner." (PMID 38786066, 2024). "To examine the anti-PDAC activity of CXCR2 CAR-T, we developed mouse models with Claudin18.2-positive tumor syngeneic grafts derived from two distinct cell lines." (PMID 38430267, 2024). "Tumor cells actively produce agonists of CXCR1 and CXCR2 to induce a neutrophil trap, preventing immune cytotoxicity and protecting tumors from CTL and NK cell attacks." (PMID 38474175, 2024). "To further investigate the effect of CXCR1 expression in tumor growth, we carried out RNA sequencing analysis of MDA-PCa-2b-Vec, MDA-PCa-2b-CXCR1, and MDA-PCa-2b-CXCR2 cells." (PMID 39766038, 2024). "Understanding the complex interactions between IL-8, CXCR1, and CXCR2 within the TME is crucial for developing targeted therapeutic strategies for PCa and addressing tumour progression, dissemination, and treatment resistance." (PMID 39199570, 2024). "Crucially, MDSCs are recruited to tumor sites via various chemokine axes, such as CCL8/CCR2, CCL5/CCR5, CXCL5/CXCR2, and CXCL12/CXCR4." (PMID 39769501, 2024). "Our pseudotime analysis suggests a developmental trajectory of neutrophils that progresses from the healthy subtype to the tumor-specific population and finally a metastasis-specific population; a lineage that is largely driven by IL1β/CXCL8/CXCR2 axis." (PMID 38358352, 2024). "Tumors of CXCR2 KO mice had elevated CXCL13 levels to recruit B cells and B cell-derived CXCL11 in turn attracted CXCR3+ T cells into the tumor." (PMID 38786066, 2024). "In tumor-bearing mice, pharmacologic inhibition of PAD4 with the selective small molecule inhibitor JBI-589 can result in reduced CXCR2 expression and block neutrophil chemotaxis." (PMID 38291476, 2024). "We applied quantitative PCR to determine the expression of 14 genes including CXCR2, SAA, COX1 and COX2, PPAR-α, -δ and -γ, Gro-α and -γ, IL8, p21, c-myc, CD44 and CSF1 in tumor and adjacent normal mucosa of 21 CRC patients." (PMID 38891062, 2024). "The combination of the CXCR2 antagonist SB225002 with PD1 blockade and PI improves tumor control and mouse survival." (PMID 39397001, 2024). "Another strategy is the generation of CAR-T cells expressing enzymes against tumor stroma (e.g., heparanase) or chemokine receptors (e.g., CXCR1 and CXCR2) matching tumor chemokines and promoting infiltration." (PMID 38201305, 2024). "Targeting CXCR2 with a selective inhibitor promoted apoptosis, senescence, EMT, and suppressed cancer cell proliferation, which led to the pronounced inhibition of tumor growth." (PMID 39061147, 2024). "Another approach to recruiting T cells into tumor is to use constructs expressing a chemokine receptor, such as CCR2, CCR2b, CXCR3, CCR4, CCR7, CXCR2, or CXCR4, which can interact with the relevant tumor-derived chemokine." (PMID 38927974, 2024). "In brief, chemokine signaling is crucial for tumor angiogenesis (CXCR2 and CXCR4), immunosuppression (CXCR3 and CCR2), and tumor progression and metastasis (CCR5 and CXCR6)." (PMID 39456552, 2024). "Together, the ectopic CXCR2 expression promoted the survival of CAR-T cells and enhanced their anti-tumor efficacy." (PMID 38430267, 2024).
tumor (continued). "In the PANC02 cell-derived tumor model, there was an increase in infiltration of CD4 + T cells in the CXCR2 CAR-T group." (PMID 38430267, 2024). "Meanwhile, CXCR2, produced by tumors, induces neutrophil extracellular traps that interfere with immune cytotoxicity; thus, inhibiting CXCR2 may significantly reduce neutrophil infiltration and enhance anti-tumor T cell activityvia promoting CD8 T cell activation." (PMID 38807380, 2024). "Owing to their role in promoting angiogenesis, CXCR1 and CXCR2 have been correlated with the development, invasion and metastasis of OSCC tumours." (PMID 38426619, 2024). "CXCR2 expression was previously shown to correlate with EMT and the reorganization of the tumor microenvironment in both C4-2B and LNCaP cells." (PMID 39766038, 2024). "Evidently, the overexpression of CXCR2 in GPC3 CAR-T cells enhanced the in vivo trafficking, accumulation, and anti-tumor efficacy of these cells in hepatocellular carcinoma xenograft models that express high levels of CXCR2 ligands." (PMID 38217016, 2024). "The inhibition of CXCR2 using AZD5069 attenuated MDSC-mediated castration resistance and extended the anti-tumour effect of enzalutamide, which has also been investigated through the Phase 1/2 ACE trial (see Section 5.4)." (PMID 39199570, 2024). "Specifically, CAR T-cells modified to express the chemokine receptor CXCR2, which interfaces with the ligand CXCL1 present on melanoma cells, exhibited proficient migration toward the tumor microenvironment." (PMID 38612592, 2024). "The GAC is a major component in the ECM and affects many properties of the tumor; one of the mechanisms can be the recruitment of the neutrophils via the CXCL1/CXCR2 interaction." (PMID 38474175, 2024). "It was demonstrated that CXCR1 and CXCR2-modified CD70 CARs downregulated the expression of exhaustion markers on T cells and upregulated the migration of T cells in the tumor." (PMID 38201305, 2024). "We observed increased expression of receptors such as CXCR2, CXCR1, and CSF3R in TAN that have been reported to be crucial for neutrophil recruitment to the tumor parenchyma." (PMID 38358826, 2024). "Neutrophils are attracted to the tumor microenvironment through chemokine receptors, CXCR1 and CXCR2, which are expressed at high levels on the surface of neutrophils." (PMID 37869087, 2023). "In the context of CXCR2+ neutrophil depletion genetically or pharmacologically, PDAC liver metastasis was remarkably reduced, along with significantly prolonged tumor-free survival of PDAC mouse models." (PMID 37771596, 2023). "Platelets activate the granulocyte-expressed receptor CXCR2 by secreting the chemokine CXCL7 (Ppbp gene) and recruiting granulocytes, contributing to tumor cell extravasation from the blood." (PMID 37994159, 2023). "Multiplexed IF staining showed that CXCL6+ tumor cells were located near the SAAs+ hepatocytes in the invasive zone, which highly expressed STAT3 and C-X-C Motif Chemokine Receptor 2 (CXCR2), the receptor of CXCL635." (PMID 37337030, 2023). "Then, we analyzed the expression of CXCR2 and CCR2 on M-MDSCs and PMN-MDSCs, which were isolated from lung tissues of 4T1 tumor-bearing mice." (PMID 37268941, 2023). "As inflammatory immune cells, neutrophils alter the tumor microenvironment by expressing chemokine receptors CXCR1 and CXCR2." (PMID 37480143, 2023). "As previously reported, tumor-generated IL-8 can attract M-MDSCs and G-MDSC (granulocytic-MDSC) from peripheral blood via CXCR1 and CXCR2, thus facilitating the extrusion of NETs, which can be blocked by the specific CXCR1/2 inhibitor reparixin." (PMID 38023616, 2023). "Tumor-released IL-1α accelerates the progression of HCC by promoting MDSCs recruitment and infiltration in spleen and tumor via CXCR2 and suppressing the capacity of CTL." (PMID 37217620, 2023).